GGCX (gamma-glutamyl carboxylase)
Diseases named in the same sentence as GGCX in open-access papers:
GGCX is named in the same sentence as 54 diseases in open-access papers, as found by Europe PMC text mining. Sharing a sentence is not in itself a finding about the gene and the disease. The quoted sentences say what the papers report.
factor deficiency (5 papers, 2017 to 2024). "Homozygous mutations in GGCX cause vitamin K-dependent clotting factor deficiency (MIM #277450) as well as pseudoxanthoma elasticum (MIM #264800), an ectopic mineralization disorder." (PMID 31727138, 2019). "Mutations in the encoding GGCX gene are associated with multiple phenotypes, amongst which vitamin K-dependent coagulation factor deficiency (VKCFD1) is best known." (PMID 28125048, 2017). "The panel also has GGCX, whose pathogenic variants were first linked to multiple vitamin K-dependent clotting factor deficiency (VKCFD1; OMIM #277450), an autosomal recessive disorder characterized by a mild to severe bleeding tendency and a predisposition to thrombotic events." (PMID 39399214, 2024). "Mutations of GGCX encoding an enzyme involved in the metabolism of Gla proteins may also cause an AR pseudoxanthoma elasticum-like disorder with multiple coagulation factors deficiency, and at times with vascular abnormalities, including cerebral aneurysms or pulmonary artery stenosis." (PMID 36834577, 2023). "There are two variants to vitamin K-dependent clotting factor deficiency VKDCF; VKDCF1, associated with point mutations in the gamma-glutamyl carboxylase gene (GGCX), and VKDCF2, which results from point mutations in the vitamin K epoxide reductase gene (VKORC1)." (PMID 28388959, 2017). "This study examined five affected individuals from three unrelated families with phenotypes consistent with PXE, with or without vitamin K-dependent coagulation factor deficiency, who were negative for variants in ABCC6 but carried biallelic pathogenic or likely pathogenic variants in the GGCX gene." (PMID 39399214, 2024).
Pseudoxanthoma elasticum (4 papers, 2017 to 2026). "Mutations in GGCX also cause mineralization phenotypes in skin such as Pseudoxanthoma elasticum (PXE)-like phenotype, and/or cardiac abnormalities, and/or skeletal defects in several patients but interestingly not in all." (PMID 35054981, 2022). "Pseudoxanthoma elasticum (PXE) is driven primarily by biallelic ABCC6 variants, with overlapping ectopic-mineralization phenotypes from ENPP1 and GGCX." (PMID 41511357, 2026). "Gamma-glutamyl carboxylase (GGCX) gene mutation causes GGCX syndrome (OMIM: 137167), which is characterized by pseudoxanthoma elasticum (PXE)-like symptoms and coagulation impairment." (PMID 28494010, 2017).
asthenozoospermia (3 papers, 2019 to 2024). "An SNP in the human GGCX gene has been associated with asthenozoospermia." (PMID 35252193, 2022). "To check whether mutations of human VKD MGP and GGCX affect male fertility, we screened for potential mutations in the exons of MGP and GGCX in a cohort of 199 patients with idiopathic asthenozoospermia and 110 fertile controls." (PMID 30981116, 2019).
breast carcinoma (3 papers, 2014 to 2021). "To mechanistically address the role of vitamin K and γ-carboxylation in breast cancer, we screened a panel of breast cancer cell models for GGCX, VKORC1, and VKORC1L1 expression." (PMID 31040920, 2019). "Further studies to evaluate the function of UBIAD1 in relation to cellular K1 and K2 content and GGCX activity in breast cancer cells are ongoing to test this model." (PMID 31040920, 2019). "Using TissueScan arrays representing 4 normal tissues and 44 breast cancers, we confirmed up-regulation of GGCX and VKORC1L1 in a subset of tumors beginning as early as Stage IIA." (PMID 31040920, 2019). "Because GGCX-mediated γ-carboxylation requires vitamin K, these data support the concept that vitamin K status has clinical relevance for breast cancer patients." (PMID 31040920, 2019). "Given the TCGA data indicating that expression of vitamin K pathway genes correlates with poor survival in breast cancer patients, we hypothesized that GGCX activation leading to γ-carboxylation would promote aggressive phenotypes including acquisition of stem cell properties." (PMID 31040920, 2019). "To explore the relevance of γ-carboxylation in breast cancer, we first analyzed datasets from The Cancer Genome Atlas (TCGA) and found that approximately 25% of 1098 invasive breast cancers exhibit amplification or up-regulation of GGCX, VKORC1, and/or VKORC1L1." (PMID 31040920, 2019). "All three genes involved in the vitamin K cycle (GGCX, VKORC1, and VKORC1L1) are expressed in normal mouse mammary gland yet there is no published data regarding their expression in human breast or breast cancer." (PMID 31040920, 2019). "Similar gene expression results were found in control MG and breast cancer (BC) samples, with heterogeneous levels of GRP-F1, MGP, GGCX, and VKOR and increased expression of OPN and TNFα in cancer cases." (PMID 24949434, 2014). "Interestingly, K1 increased GGCX activity and promoted synthesis of γ-carboxylated proteins in TNBC cells but not in normal mammary epithelial cells or hormone responsive breast cancer cells." (PMID 31040920, 2019). "To gain insight into the potential impact of the vitamin K pathway in breast cancer, we annotated expression of GGCX, VKORC1, and VKORC1L1, profiled GLA protein modifications, and directly compared the effects of K1 and K2 in multiple breast cancer model systems." (PMID 31040920, 2019).
PXE-like syndrome (3 papers, 2012 to 2019). "A somewhat similar convergence exists between the PXE-like syndrome in which GGCX mutations lead to insufficient MGP carboxylation (activation) and the classic inherited PXE." (PMID 23248644, 2012). "The genetic overlap between VKCFD1 and PXE-like syndrome, though a distinct phenotypic presentation, may be explained by the fact that mutations causing PXE-like syndrome seem to typically occur in exons 8, 10, and 12 of the GGCX gene, while no such mutations have been found so far in VKCFD1." (PMID 31052252, 2019).
hepatocellular carcinoma (2 papers, 2014 to 2021). A malignant tumor that arises from hepatocytes. "However, increased gene expression might not reflect protein functionality, and impaired GGCX activity has been associated with insufficient γ-carboxylation of prothrombin in cancers, while levels of GGCX mRNA have been shown either increased or heterogeneous among hepatocellular carcinomas." (PMID 24949434, 2014).
invasive breast carcinoma (2 papers, 2019 to 2023). A carcinoma that infiltrates the breast parenchyma. "The highest expressions of GGCX and VKORC1 have been observed in triple negative breast cancer cell lines and in advanced stages of disease, such as invasive breast cancers, when compared with normal mammary glands." (PMID 37670241, 2023). "Collectively, the available genomic and proteomic data suggest that the vitamin K-dependent pathway genes, GGCX, VKORC1, and VKORC1L1, are present in normal mammary gland but up-regulated in a subset of invasive breast cancers that are characterized by poor overall survival." (PMID 31040920, 2019).
schizophrenia (2 papers, 2014 to 2023). A major psychotic disorder characterized by abnormalities in the perception or expression of reality. "MYO5B gene and GGCX gene show strong associations with schizophrenia." (PMID 37510227, 2023).
triple-negative breast carcinoma (2 papers, 2019 to 2023). An invasive breast carcinoma which is negative for expression of estrogen receptor (ER), progesterone receptor (PR), and human epidermal growth factor receptor 2 (HER2). "qPCR results indicated highest expression of GGCX, VKORC1, and VKORC1L1 in triple negative breast cancer (TNBC) cell lines, Hs578T, MDA-MB-231 and SUM159PT, and in advanced stage disease." (PMID 31040920, 2019).
uremia (2 papers, 2018 to 2025). A clinical syndrome associated with the retention of renal waste products or uremic toxins in the blood. "Pre-clinical studies indicate an impact of uremia on tissue levels of vitamin K and on the activity of GGCX, the key enzyme involved in activation of VKDPs." (PMID 30103541, 2018). "However, through a currently unidentified mechanism, the activity of GGCX is reduced in experimental uremia, thereby contributing to the promotion of vascular calcifications." (PMID 40202064, 2025).
bladder cancer (1 paper, 2016). "The GGCX gene is expressed in the bladder, but has not been previously associated with bladder cancer in univariate GWAS." (PMID 27999618, 2016).
bleeding disorder (1 paper, 2022). "Vitamin K dependent coagulation factor deficiency type 1 (VKCFD1) is a rare hereditary bleeding disorder caused by mutations in γ-Glutamyl carboxylase (GGCX) gene." (PMID 35054981, 2022). "Mutations in GGCX gene cause a rare hereditary bleeding disorder called Vitamin K dependent coagulation factor deficiency type 1 (VKCFD1; OMIM #277450)." (PMID 35054981, 2022).
breast tumors (1 paper, 2019). "Publicly available data on the Human Protein Atlas confirm that GGCX protein is expressed in normal breast epithelium and that both in situ and invasive ductal and lobular breast tumors express the enzyme at high levels." (PMID 31040920, 2019). "In addition, TCGA data indicated that the subset of patients whose breast tumors exhibit genomic amplification or up-regulation of GGCX, VKORC1, and VKORC1L1 had significantly reduced overall survival." (PMID 31040920, 2019).
cerebral artery aneurysms (1 paper, 2022). "These mutations involving the GGCX gene resulted in ectopic mineralization marked by loss of skin elasticity as well as cerebral artery aneurysms." (PMID 36292250, 2022).
cholangiocarcinoma (1 paper, 2020). A carcinoma that arises from the intrahepatic biliary tree (intrahepatic cholangiocarcinoma) or from the junction, or adjacent to the junction, of the right and left hepatic ducts (hilar cholangiocarcinoma). "However, CD36, GGCX, UBASH3B, DBN1, PTTG1, CCNA2, and SPATS2 are found in other tumors to regulate tumor progression, which may also regulate cholangiocarcinoma progression and affect the recurrence of CCA." (PMID 32071556, 2020).
coagulation factor deficiency (1 paper, 2022). "While rodent model data appear negative, the existence of a PXE-like disorder with coagulation factor deficiency–caused by GGCX (Gamma-Glutamyl Carboxylase) mutations–where VK-dependent carboxylation is (nearly) abolished suggests an important role for VK in mineralization homeostasis." (PMID 35317004, 2022).
Cognitive impairment (1 paper, 2021). Abnormal cognition is characterized by deficits in thinking, reasoning, or remembering. "Since vitamin K has multiple modes of action, other mechanisms independent of GGCX could be involved in its effects on cognitive impairment." (PMID 35174198, 2021).
hemorrhage (1 paper, 2019). Loss of blood from the vascular compartment to the exterior or into nonvascular body space as a result of rupture or severance of the blood vessels. "To investigate the reproductive function of the VKD proteins GGCX and MGP in vivo, we established a warfarin-induced VK2-deficient rat model by using a modified protocol supplemented with VK1 to avoid VK1-deficiency-induced hemorrhage." (PMID 30981116, 2019).
Infertility (1 paper, 2022). "GGCX in the Sertoli cells plays an important role in mouse infertility." (PMID 36313743, 2022). "Moreover, mice with Sertoli cell-specific KO γ-glutamyl carboxylase (GGCX) present late-onset infertility accompanied by the appearance of multinucleated and apoptotic germ cells in the seminiferous tubules." (PMID 36313743, 2022).
Intraventricular hemorrhage (1 paper, 2025). Bleeding into the ventricles of the brain. "Although vitamin K-dependent coagulation factor deficiency is known to be molecularly associated with mutations in the GGCX or VKORC1 genes, one study indicated that the VKORC1-wildtype type increases the risk of intraventricular hemorrhage in infants." (PMID 41361303, 2025).
ischemic stroke (1 paper, 2023). A stroke disorder caused by obstruction of blood flow to the brain, due to thrombotic (local blood clot formation) or embolic (due to a blood clot or other material traveling from another site) event. "This is the first study on patients with ischemic stroke that has examined the role of polymorphisms in the VKORC1, CYP4F2, and GGCX genes together." (PMID 37653796, 2023).
Keutel syndrome (1 paper, 2017). Keutel syndrome is characterized by diffuse cartilage calcification, brachytelephalangism, peripheral pulmonary artery stenoses and facial dysmorphism. "Brachytelephalangy of the fingers is a distinct characteristic of Keutel syndrome (OMIM#245150), an autosomal recessive disorder caused by mutations in MGP, a VKDP that is carboxylated by GGCX." (PMID 28125048, 2017).
kidney failure (1 paper, 2018). An acute or chronic condition that is characterized by the inability of the kidneys to adequately filter the blood. "In rat kidney failure, activity of the rate-limiting enzyme in the vitamin K cycle—gamma-glutamyl carboxylase (GGCX)—was reduced, resulting in increased serum ucMGP levels." (PMID 30029499, 2018).
leukemia (1 paper, 2024). A malignant (clonal) hematologic disorder, involving hematopoietic stem cells and characterized by the presence of primitive or atypical myeloid or lymphoid cells in the bone marrow and the blood. "We previously showed that the VK2-2,3 epoxide, an intracellular metabolite of VK2 induced by gamma-glutamyl carboxylase (GGCX), covalently binds to Bak, directly leading to Bak-mediated apoptosis in leukemia cells." (PMID 39052583, 2024).
lung carcinoma (1 paper, 2017). "Hence, NFIX with IL6ST, TIMP1, ITGB1, PTCH1, GGCX and NFAT5 genes may regulate the migration and invasion process and they could serve as potential therapeutic targets in patients with lung cancer to predict survival and improve prognosis." (PMID 28871224, 2017).
male infertile (1 paper, 2019). "In summary, our study demonstrates that the VK2-dependent protein MGP and its carboxylation enzyme GGCX play an essential role in epididymal sperm maturation and male fertility in rats and that the mutation of GGCX is associated with one form of human male infertility." (PMID 30981116, 2019). "Our results suggest that the VKD GGCX-MGP system could be a target for clinical screening and potentially for the treatment of idiopathic male infertile cases." (PMID 30981116, 2019).
malignant neoplasm of prostate (1 paper, 2022). "Prediction based on colocalization analysis suggests that inhibition of GGCX may lower CAD-risk, but according to the PheWAS it is associated with an increase risk of malignant neoplasm of prostate (PPheWAS = 3.06 × 10–9)." (PMID 35246263, 2022).
migraine (1 paper, 2020). "Gene-rich association loci such as VAMP5-VAMP8-GGCX (CAD) and LRP1-STAT6-SDR9C7 (migraine) colocalized only with GGCX and LRP1 in arterial tissues." (PMID 31917787, 2020).
osteoporosis (1 paper, 2019). A condition of reduced bone mass, with decreased cortical thickness and a decrease in the number and size of the trabeculae of cancellous bone (but normal chemical composition), resulting in increased fracture incidence. "GGCX in other cell lineages or in other tissues might play a protective role for osteoporosis." (PMID 31212662, 2019).
Stroke (1 paper, 2011). Sudden impairment of blood flow to a part of the brain due to occlusion or rupture of an artery to the brain. "The second paper evaluated the roles of VKORC1, gamma-glutamyl carboxylase (GGCX), calumenin (CALU), and cytochrome P450 2C9 (CYP2C9) in warfarin maintenance dose on Japanese stroke sufferers." (PMID 22135769, 2011).
Ventricular arrhythmia (1 paper, 2022). "In Human Phenotype Ontology, CTSK, GGCX and KCNH2, have been linked to bone-related conditions, coagulation defects and ventricular arrhythmia respectively." (PMID 35246263, 2022).
tumor (5 papers, 2014 to 2025). "ScRNA‐seq data show that vitamin K cycle genes(NQO1, UBIAD1, GGCX, VKORC1, VKORC1L1) are specifically expressed in tumor cells." (PMID 41028931, 2025). "Further studies examining the levels of GGCX and VCOR1 in the tumor microenvironment are meritorious, as well as developing suitable mouse models to genetically manipulate these rate-limiting enzymes for γ-carboxylation." (PMID 29176978, 2017). "Expression levels of GRP splice transcripts were determined in control and cancerous tissues and correlated with gene expression of MGP, GGCX, VKOR, and the tumor markers OPN and TNFα." (PMID 24949434, 2014). "Staining for GGCX was localized only in tumor cells indicating that stromal cells are unlikely to contribute to protein γ-carboxylation." (PMID 31040920, 2019). "Both of the enzymes required for γ-carboxylation, namely GGCX and VCOR1, appear to be broadly expressed in cells, including a variety of cells that express Gas6 and contribute to the tumor microenvironment, such as monocytic cells (macrophages) and cancer cells themselves." (PMID 29176978, 2017). "Interestingly, the same heterogeneous pattern was found for MGP, GGCX, and VKOR, while OPN and TNFα were found clearly upregulated in tumor samples." (PMID 24949434, 2014). "However, higher levels of GRP-F1, MGP, GGCX, and VKOR were found in BC samples that include microcalcifications, suggesting an upregulation associated with calcification, but not necessarily with tumor development." (PMID 24949434, 2014).
cancer (4 papers, 2014 to 2024). A tumor composed of atypical neoplastic, often pleomorphic cells that invade other tissues. "The first possible explanation is that the activity of the gamma-glutamyl carboxylase decreases in cancer tissue because of the expression of an abnormal, less functional gamma-glutamyl carboxylase protein." (PMID 38732309, 2024). "Although increasing sample sets, not yet available in our laboratory, would be required to clearly establish a relation between GRP-F1 expression levels and cancer development, it is interesting to note that expression pattern of GGCX, VKOR, and MGP was found highly similar to that of GRP-F1." (PMID 24949434, 2014).
cardiovascular diseases (1 paper, 2023). "Single nucleotide polymorphisms (SNPs) in the VKORC1, CYP4F2, and GGCX genes have been linked to clinical outcomes, such as bleeding and cardiovascular diseases." (PMID 37653796, 2023).
GGCX also shares sentences with these, for which no sentence is quoted: arteriopathy (1 paper); autoimmune disease (1); beta thalassemia (1); calcification (1); cerebral aneurysms (1); chronic kidney disease (1); congenital dyserythropoietic anemia (1); cutis laxa (1); Generalized arterial calcification of infancy (1); Glucose intolerance (1); hemoglobinopathies (1); Obesity (1); Paget’s disease of the bone (1); Pigmentary retinopathy (1); Pulmonary artery stenosis (1); pulmonary embolism (1); sickle cell disease (1); type 1 diabetes (1); Williams-Beuren syndrome (1); X-linked chondrodysplasia punctata (1).